PTPN13 (protein tyrosine phosphatase non-receptor type 13)
Description:
Tyrosine phosphatase which negatively regulates FAS-induced apoptosis and NGFR-mediated pro-apoptotic signaling. May regulate phosphoinositide 3-kinase (PI3K) signaling through dephosphorylation of PIK3R2.
Synonyms: FAP-1; PNP1; PTP1E; PTPL1; PTP-BAS; PTP-BL; PTPLE; hPTP1E
Tractability: Small molecule: a structure with a bound ligand is known; a high-quality ligand is known; it has a high-quality binding pocket; it belongs to a druggable protein family. Antibody: its Gene Ontology location is reachable by antibodies, with high confidence; the Human Protein Atlas places it where antibodies can reach. PROTAC: ubiquitination databases record sites on it; a small molecule that binds it is known.
Target class: Tyrosine protein phosphatase; Enzyme; Phosphatase; Protein Phosphatase
Gene: Protein-coding gene on chromosome 4 (86,593,944 to 86,815,180, forward strand). Ensembl gene ENSG00000163629.
Subcellular location: Cytoplasm, cytoskeleton; Nucleus; Cell projection, lamellipodium
Subcellular location (Human Protein Atlas): Plasma membrane; Primary cilium; Basal body; Cytosol; Primary cilium transition zone
Pathways (Reactome):
Signal Transduction: RND1 GTPase cycle; RND2 GTPase cycle; RND3 GTPase cycle
Immune System: Interleukin-37 signaling
Metabolism: Synthesis of PIPs at the plasma membrane
Gene Ontology:
Molecular function: phosphatidylinositol 3-kinase regulatory subunit binding; protein binding; protein tyrosine phosphatase activity
Biological process: negative regulation of protein phosphorylation; peptidyl-tyrosine dephosphorylation; protein dephosphorylation; regulation of phosphatidylinositol 3-kinase/protein kinase B signal transduction; negative regulation of excitatory synapse assembly; cellular response to toxic substance
Cellular component: cytoplasm; extracellular exosome; lamellipodium; nucleus; plasma membrane; nucleoplasm; cell body; cytoskeleton
Genetic constraint (gnomAD): Loss-of-function variants: 137 observed, 214.25 expected, observed/expected ratio (o/e) 0.64, 90% interval 0.56 to 0.74. The upper end of that interval is the gene's LOEUF score, 0.74, which puts it in group 3 of 6, group 1 being the genes least tolerant of losing a copy. Missense variants: 2,439 observed, 2,606.2 expected, observed/expected ratio (o/e) 0.94, 90% interval 0.9 to 0.97. Synonymous variants: 846 observed, 915.83 expected, observed/expected ratio (o/e) 0.92, 90% interval 0.87 to 0.98.
Cancer hallmarks: escaping programmed cell death (suppresses); escaping programmed cell death (promotes); invasion and metastasis (suppresses)
Homologues: Orthologues: chimpanzee PTPN13 (99% identical), macaque PTPN13 (97% identical), dog PTPN13 (90% identical), pig PTPN13 (87% identical), rabbit PTPN13 (86% identical), mouse Ptpn13 (80% identical), guinea pig PTPN13 (80% identical), rat Ptpn13 (79% identical), tropical clawed frog ptpn13 (59% identical), zebrafish ptpn13 (27% identical). Paralogues in human: PTPRB (13% identical), PTPRD (10% identical), PTPRJ (10% identical), PTPRF (9% identical), PTPRS (9% identical), PTPRZ1 (9% identical), PTPRH (8% identical), PTPRT (8% identical), PTPN23 (8% identical), PTPRK (8% identical), PTPRM (8% identical), PTPRO (8% identical), and 23 more.
Diseases named in the same sentence as PTPN13 in open-access papers:
PTPN13 is named in the same sentence as 86 diseases in open-access papers, as found by Europe PMC text mining. Sharing a sentence is not in itself a finding about the gene and the disease. The quoted sentences say what the papers report.
breast carcinoma (20 papers, 2004 to 2026). "The main tumor suppressors downregulated in AT are PCDH10 (log2FC − 4.76), a protocadherin whose promoter is methylated in diffuse large B-cell lymphomas or PTPN13 (log FC: − 2.84) an inhibitor of FAS-induced apoptosis associated with aggressive breast cancer." (PMID 34183044, 2021). "In breast cancer (n = 291 samples), we showed that high PTPN13 expression, measured by RT/PCR, is associated with better prognosis (p = 0.01 and RR = 0.48 in multivariate analysis)." (PMID 33322542, 2020). "Wei and collaborators found that a nucleotide polymorphisms in PTPN13 that is associated with colorectal cancer susceptibility also influences the risk of breast cancer in a Chinese Han population." (PMID 31938048, 2020). "Our current findings suggest that ErbB2 transmembrane mutations (like neu (rat) and the human 655 polymorphism) synergize with decreased/lost PTPN13, allowing breast cancer progression via a mechanism involving increased ErbB2/EphrinB1 signaling." (PMID 22279592, 2012). "We have shown that the PTP13 inhibition of breast cancers is associated with a stabilization of cell-junctions; it would now be important to investigate whether such PTPN13 effects are found in all these tumor types where PTPN13 expression is associated with a good prognosis." (PMID 31938048, 2020). "The association of oncogene kinases (ErbB2, Src), a signaling transmembrane ligand (EphrinB1) and a phosphatase tumor suppressor (PTPN13) suggest that EphrinB1 may be a relevant therapeutic target in breast cancers harboring ErbB2-activating mutations and decreased PTPN13 expression." (PMID 22279592, 2012). "We also demonstrated that PTPN13 mRNA expression is an independent prognostic marker of increased overall survival in breast cancer." (PMID 37895093, 2023). "We previously reported the first evidence that PTPN13 negatively regulates tumor growth in human breast cancer cell lines." (PMID 37895093, 2023). "Accumulating evidence suggests that PTPN13 is involved in cancers such as colorectal cancer, breast cancer, lymphomas, and head and neck squamous cell carcinoma." (PMID 33051595, 2021). "Altogether these results demonstrate that PTPN13 inhibits breast cancer cell migration through its phosphatase activity." (PMID 31938048, 2020). "We chose MDA-MB-231 breast cancer cells because of their very low endogenous PTPN13 levels, high invasive capacity and hormone-independency." (PMID 31938048, 2020). "Then, using gain-of-function isogenic clones of MDA-MB-231 (HER2-negative and hormone-independent) breast cancer cells we demonstrated that PTPN13 phosphatase activity inhibits invasion and promotes intercellular adhesion." (PMID 31938048, 2020). "We now extended our knowledge about PTPN13 effect on cell invasiveness to hormone-independent breast cancer models (i.e., HER2-positive and TNBC tumors)." (PMID 31938048, 2020). "In a second study, in which we analyzed 24 breast cancer samples by immunohistochemistry (IHC), we observed a progressive decrease in PTPN13 expression from normal to metastatic tissue samples." (PMID 33322542, 2020). "PTPN13 is considered an independent biomarker of good prognosis in several solid tumor types, such as breast cancer, HGSOC, and HCC." (PMID 33322542, 2020). "We now used KM Plotter data 36 to analyze the overall survival of patients with breast cancer according to the tumor PTPN13 RNA level (high/low), and confirmed the prognostic interest of PTPN13." (PMID 31938048, 2020). "Altogether, these results indicate than PTPN13 catalytic activity positively regulates desmosome assembly and/or stability in breast cancer cells." (PMID 31938048, 2020). "Our group described PTP-BL role in adipocyte differentiation, and also reported the first evidence of PTPN13 negative regulation of tumor growth through an anti-growth factor effect in human breast cancer cell lines incubated with anti-estrogens." (PMID 29221157, 2017).
breast carcinoma (continued). "While Her2, Luminal A, Luminal B breast cancers and normal breast samples express relatively high levels of PTPN13, basal-like (BL) tumors express significantly lower levels of PTPN13 mRNA (p = 0.00044 for basal vs. normal)." (PMID 22279592, 2012). "Here we show that PTPN13 regulates a new signaling complex in breast cancer consisting of ErbB2, Src, and EphrinB1." (PMID 22279592, 2012). "Our data further suggest that breast cancers with elevated ErbB2 expression and compromised PTPN13 expression and/or function would benefit the most from this type of dual targeting." (PMID 22279592, 2012). "We describe a complex consisting of ErbB2, Src, EphrinB1 and PTPN13 that mediates EphrinB1 phosphorylation and downstream signaling in breast cancer cells." (PMID 22279592, 2012). "In addition, PTPN13 mRNA expression is an independent prognostic marker of increased overall survival in breast cancer 23, in hepatocellular carcinoma 24, lung cancer 16 and in high grade serous ovarian cancer." (PMID 31938048, 2020). "Conversely, our group demonstrated that PTPN13 inhibits PI3K in MCF7 breast cancer cells." (PMID 33322542, 2020). "In triple negative breast cancer, PTPN13, the transcriptional target gene of SMYD2, could be phosphorylated by SMYD2 and link SMYD2 to breast cancer associated signaling pathways, such as ERK, and mTOR signaling pathways, further affected breast cancer growth." (PMID 31548876, 2019). "In addition, we have identified a novel SMYD2 transcriptional target gene, PTPN13, which links SMYD2 to other known breast cancer associated signaling pathways, including ERK, mTOR, and Akt signaling via PTPN13 mediated phosphorylation." (PMID 29487338, 2018). "In addition, PTPN13 mRNA expression is an independent prognostic marker of increased overall survival in breast cancer, in hepatocellular carcinoma, and lung cancer." (PMID 29221157, 2017). "Decreased PTPN13 expression correlates with decreased overall survival in breast cancer." (PMID 22279592, 2012). "Decreased PTPN13 expression in BL breast cancers supports a tumor suppressive role for PTPN13." (PMID 22279592, 2012). "Thus, we analyzed a gene expression array from 200 early stage breast cancers and 7 normal breast samples for PTPN13 with particular attention to subtype specificity." (PMID 22279592, 2012). "We also examined PTPN13 protein expression in sub-type defined breast cancer cell lines." (PMID 22279592, 2012). "In the context of breast cancer where decreased PTPN13 expression correlates with poor survival, defining the pathways activated in the absence of PTPN13 may identify critical targets for therapeutic intervention and improve survival." (PMID 22279592, 2012). "Importantly, decreased PTPN13 expression in breast cancer correlates with decreased overall survival." (PMID 22279592, 2012). "Additionally, PTPN13 is frequently epigenetically inhibited in breast cancer." (PMID 39208653, 2024). "In addition, we confirmed that PTPN13 is a SMYD2 transcriptional target gene in TNBC cells, which may link SMYD2 to other breast cancer associated signaling pathways, including ERK, mTOR, and Akt signaling." (PMID 29487338, 2018). "With respect to breast cancer, ErbB2/EphrinB1 signaling may be most relevant in tumors with high ErbB2 expression and either low/absent PTPN13 expression or those harboring PTPN13 functional mutations." (PMID 22279592, 2012). "However, given its affects on EphrinB1 phosphorylation in breast cancer cells, we speculated that a reduction in PTPN13 expression or function may be a common and, more importantly, a key alteration in other epithelial cancers." (PMID 22279592, 2012). "PTPN13 can dephosphorylate ERK and AKT in tumor cells and inhibit breast cancer by directly dephosphorylating SRC." (PMID 36096985, 2022). "Other studies have reported that PTPN13 expression is markedly lower in LAC than adjacent normal tissue and is an independent prognostic factor of favorable outcome for breast cancer patients." (PMID 33051595, 2021).
breast carcinoma (continued). "Here, we used a genetic approach, by crossing mice that lack PTPN13 catalytic activity 9 with transgenic mice that overexpress human HER2 and are more prone to breast cancer." (PMID 31938048, 2020). "We recently demonstrated that human protein tyrosine phosphatase (PTP) L1, a large cytoplasmic phosphatase also known as PTP-BAS/PTPN13/PTP-1E, is a negativeregulator of IGF-1R/IRS-1/Akt path-way in breast cancer cells." (PMID 23514123, 2013). "To test the effects of decreased/lost PTPN13 on EphrinB1 phosphorylation, we examined two BL breast cancer cell lines: MDA-MB231, expressing nearly undetectable PTPN13 protein, and MDA-MB468, expressing endogenous PTPN13 protein." (PMID 22279592, 2012). "It has reported that PTPL1/PTPN13 regulated breast cancer cell aggressiveness through a direct inactivation of Src kinase and PTPN12 inhibits breast cancer metastasis through multiple targets including EGFR1, Her2 and Src kinase." (PMID 22394684, 2012). "PTPN13/PTPL1 promoter methylation has been confirmed in a variety of malignancies including non-small cell lung cancer, ovarian cancer, prostate cancer, and breast cancer." (PMID 38766487, 2024). "However, most PTPN family members function as tumor suppressors in breast cancer, including PTPN2, PTPN4, PTPN6, PTPN9, PTPN13, PTPN14, and PTPN23." (PMID 35957898, 2022). "Moreover, NECL2 and NECL4 can interact with PTPN13 to inhibit the ERBB2/ERBB3 pathway in colorectal cancer (Caco-2), breast cancer (MCF7), and human embryonic kidney (HEK293) cells." (PMID 33322542, 2020). "Finally, we found that PTPN13 silencing in poorly invasive, hormone-dependent MCF7 breast cancer cells increases the growth of MCF7 cell xenografts in the mammary fat pad of athymic mice, through Src dephosphorylation." (PMID 31938048, 2020). "In conclusion, the ephrinB1/ERBB2 (in breast cancer) and ephrinB1/ERBB1 (in head and neck cancer) complexes induce MAPK pathway activation and are positively regulated by SRC and negatively regulated by PTPN13." (PMID 33322542, 2020). "In breast cancer cell lines, we showed that PTPN13 has a negative effect, via insulin receptor substrate 1 (IRS1) dephosphorylation, on the activation of PI3K, one of the driver pathways in ovarian cancer." (PMID 29221157, 2017). "Thus, we hypothesized that the synergy between decrease PTPN13 and increased ErbB2 activation that drives tumor growth and invasion is mediated via EphrinB1 and, further, that EphrinB1-mediated signaling is enhanced in breast cancers with compromised PTPN13 expression." (PMID 22279592, 2012). "In the breast cancer cell lines studied, low/absent PTPN13 together with elevated ErbB2 expression correlate with enhanced ErbB2/EphrinB1 association as well as increased EphrinB1 and Erk1/2 phosphorylation." (PMID 22279592, 2012). "Taken together, these data suggest that in breast cancer cell lines with low/absent PTPN13 expression, and high ErbB2 expression, EphrinB1 phosphorylation is elevated as is its association with ErbB2 and correlates with enhanced Erk1/2 phosphorylation." (PMID 22279592, 2012). "Our group described PTP-BL role in adipocyte differentiation 10 and reported the first evidence of PTPN13 tumor-suppressive, anti-growth factor effect, via insulin receptor substrate 1 (IRS1) dephosphorylation, in human breast cancer cell lines incubated with anti-estrogens 11-13." (PMID 31938048, 2020). "Expression of an activated ErbB2 mutant or over-expression of wildtype ErbB2 (as in Her2 breast cancers), together with decreased PTPN13 expression or function, not only enhances complex formation but also leads to EphrinB1 phosphorylation and associated downstream signaling." (PMID 22279592, 2012). "The absence of PTPN13, as occurs in BL breast cancers, affects EphrinB1 phosphorylation and likely downstream signaling, which may include components of the MAP Kinase pathway." (PMID 22279592, 2012).
breast carcinoma (continued). "Thus, complex formation in BL breast cancers is likely to occur with downstream signaling amplified in the absence of PTPN13 and over-expression of ErbB1 or other ErbB family members." (PMID 22279592, 2012). "However, PTPN13 might hinder EMT also through cell junction stabilization via its positive role on desmosome formation, as demonstrated in vitro in MDA-MB-231 breast cancer cells that overexpress PTPN13 and in vivo in a transgenic mouse model that lacks PTPN13." (PMID 33322542, 2020). "However, while PTPN13 mRNA levels in Her2, Luminal A and Luminal B breast cancers is not different than normal breast, the data do not eliminate the possibility that PTPN13 functional mutations occur in these subtypes that may result in a phenotype similar to that found in its absence." (PMID 22279592, 2012).
lung cancer (13 papers, 2013 to 2024). A malignant neoplasm involving the lung. "Nevertheless, all analyzed mutations have an inhibitory effect on PTPN13 activity, and their presence appears to be associated with poor prognosis in lung cancer (p = 0.02) and possibly in gastric cancer." (PMID 33322542, 2020). "Consistent with the observations in cultured lung cancer cells, the administration of miR-26a inhibitors caused increased PTPN13 protein levels and decreased phospho-Src levels in NSCLC xenograft tumors." (PMID 27285768, 2016). "In lung carcinoma, PTPN13 gene is frequently inactivated through the loss of either mRNA and protein expression or somatic mutation." (PMID 24191246, 2013). "In 262 patients with familial lung cancer, a non-synonymous PTPN13 exon variant (rs115836094) at 4q21.3-28.3 could be involved in carcinogenesis." (PMID 33322542, 2020). "Loss of PTPN13 correlated with poor overall survival in lung cancer patients." (PMID 27285768, 2016). "They identified PTPN13 as a new lung cancer pivotal gene and validated its prognostic importance retrospectively in four independent lung cancer datasets (n = 529 patients)." (PMID 33322542, 2020). "Overall, approximately 7–8% of lung cancer and 20% of HPV-negative HNSCC samples harbor PTPN13 mutations." (PMID 33322542, 2020). "PTPN13 (also known as FAP1, PTPL1, PTPLE, PTPBAS, and PTP1E), a putative tumor suppressor, is frequently inactivated in lung carcinoma through the loss of either mRNA or protein expression." (PMID 24191246, 2013). "Although substantial advances have been made in understanding the mechanisms that regulate its expression, the molecular mechanisms by which PTPN13 is down-regulated in lung carcinomas remain largely unexplored." (PMID 24191246, 2013). "Given that Stat3 signaling is usually activated in cancers, our findings suggest a potential mechanism for the down-regulation of PTPN13 in lung carcinoma." (PMID 24191246, 2013). "PTPN13 has been identified as a tumor suppressor gene in non‐small cell lung cancer." (PMID 38967523, 2024). "PTPN13 overexpression in a hepatocellular carcinoma cell line and PTPN13 inhibition in lung cancer cells and human umbilical endothelial cells may regulate EMT driver gene expression." (PMID 37895093, 2023). "Furthermore, Ptpn13 is a tumor suppressor gene that is frequently inactivated in non–small cell lung cancer (NSLC) (in more than 70% of NSLC), and was downregulated in our ALI and in vivo exposure to TiO2 while upregulated in in vitro condition." (PMID 32659965, 2020). "To test whether PTPN13 is a functional target of miR-26a in determining gefitinib responsiveness of lung cancer cells, we silenced PTPN13 in PC-9 cells." (PMID 27285768, 2016). "Indeed, the expression level of PTPN13 was much lower in EGFR-TKIs resistant lung cancer cell lines than BEAS-2B cells, however EGFR-TKIs sensitive cells have relatively high expression levels of PTPN13." (PMID 27285768, 2016). "Furthermore, PTPN3, PTPN6, PTPN12 and PTPN13 play tumor suppressor roles in lung cancer." (PMID 35957898, 2022). "Three of four studies on lung cancer [squamous lung cell carcinoma (LSCC), adenocarcinoma, and non-small-cell lung carcinoma (NSCLC)] found a significant decrease in PTPN13 expression in tumors compared with normal tissues." (PMID 33322542, 2020). "PTPN13 restrained anchorage‐independent growth and tumorigenicity in lung cancer via inactivation of the EGFR and HER228, participated in the lung cancer invasion and negatively correlated with cancer grade and stage 29." (PMID 28653805, 2017).